IL6 (interleukin 6)
Diseases named in the same sentence as IL6 in open-access papers (continued):
Sharing a sentence is not in itself a finding about the gene and the disease.
Peritoneal Fibrosis (continued). "In recent years, we have reported that interleukin-6 (IL-6) drives a STAT3-dependent pathway that leads to structural and functional alterations of peritoneal membrane in a mouse peritoneal fibrosis model." (PMID 34193173, 2021). "In dialysis-induced peritoneal fibrosis, MSCs are situated in an inflammatory environment of TGF-β1 and secrete IL-6 to polarize macrophages into the M2 phenotype." (PMID 33741073, 2021). "ADSCs boost the M2-polarizing IL-6 secretion when situated in an inflammatory environment of TGF-β1, explaining the therapeutic mechanism of dialysis-induced peritoneal fibrosis." (PMID 33741073, 2021). "S. epidermidis triggered IL-6-dependent Th1 expansion which activated STAT1 in peritoneal membrane and subsequent peritoneal fibrosis." (PMID 32708044, 2020). "The high levels of various proinflammatory molecules such as IL-6 and TGF-β cytokines during PD create an environment that induces a chronic inflammatory condition in the peritoneal cavity and generates peritoneal fibrosis." (PMID 26064907, 2015). "We previously reported that IL‐6 trans‐signalling activates signal transducer and activator of transcription 3 (STAT3) in human peritoneal mesothelial cells (HPMCs) and participate in the MMT process to promote peritoneal fibrosis." (PMID 38780509, 2024). "The peritoneum can be damaged by various factors, activating macrophages and neutrophils that mediate NF-κB signalling pathways via Toll-like receptors (TLRs) and release numerous inflammatory cytokines, such as IL-6, IL-1β, IL-8, and TNF-α, leading to peritoneal fibrosis." (PMID 37817984, 2023). "This response was totally IL-6 dependent, and repeatedly challenged Il6−/− mice displayed no histological evidence of peritoneal fibrosis." (PMID 24412616, 2014). "Nintedanib attenuates the expression of cytokines/chemokines, including TNF-α, IL-1β, and IL-6, monocyte chemoattractant protein-1 (MCP-1) and prevents the macrophages infiltration to the injured peritoneum in chlorhexidine gluconate (CG)-induced peritoneal fibrosis." (PMID 35164664, 2022). "Paricalcitol, an analog of vitamin D and a specific activator of vitamin D receptors (VDR), reduced PDF-induced peritoneal fibrosis in murine PD and decreased peritoneal IL-17A levels but not of other cytokines, including IL-1β, IL-2, IL-4, IL-5, IL-6, IL-10, TNF-α, IFN-γ, and TGF-β1." (PMID 32987705, 2020). "Thus, TGFβ1 promotes peritoneal fibrosis and dysfunction, PDGF-B promotes angiogenesis, IL-6 and its soluble receptor (sIL-6R) control the pattern of leukocyte recruitment during peritoneal inflammation and the IFNγ/TNFα combination promotes mesothelial cell apoptosis." (PMID 24599047, 2014). "Transfer of Th1 cells, but not naive CD4+ T cells, induced peritoneal fibrosis in Il6−/− mice." (PMID 24412616, 2014). "Consequently, IL-6 does not directly promote peritoneal fibrosis." (PMID 24412616, 2014).
thyrotoxicosis (23 papers, 2007 to 2025). A hypermetabolic syndrome caused by the elevation of thyroid hormone levels in the serum. "In the multivariate analysis, thyrotoxicosis was associated with higher IL-6 levels (odds ratio: 3.25, 95% CI: 1.97-5.36; P < 0.001).16% of patients with overt thyrotoxicosis developed thromboembolic events." (PMID 36601011, 2022). "Increased interleukin-6 levels and hyperadrenergic state induced by thyrotoxicosis are also implicated in hypercalcemia." (PMID 25878906, 2015). "Thyrotoxicosis was significantly associated with higher serum IL-6 levels." (PMID 36601011, 2022). "Thyrotoxicosis is a common clinical picture of Grave’s disease which involves autoimmune mechanisms that elevate levels of interleukin-6 (IL-6), which is a cytokine contributing to the autoimmune storm." (PMID 38892840, 2024). "Remarkably, thyrotoxicosis showed a correlation with serum interleukin (IL)-6 values, indicating that a greater inflammatory reaction exposed the patients to a higher chance of developing thyrotoxicosis." (PMID 37835009, 2023). "Transient thyrotoxicosis has been mainly described in patients admitted to the intensive care unit (ICU) and it has been associated with high interleukin 6 (IL-6) levels." (PMID 38001898, 2023). "Several previous reports have tried to address thecontribution of thyrotoxicosis to the rise in inflammatory cytokines such as IL-1,IL-6, IL-10, and TNF-alpha." (PMID 19343192, 2009). "IL-6 seems to be correlated with the severity of thyrotoxicosis." (PMID 35454008, 2022). "We hypothesized that reactive oxygen intermediates, that were induced by thyrotoxicosis, act as a signal for the release of cytokines like IL-6, IL-10, and TNF-alpha." (PMID 19343192, 2009). "IL-6 was inversely related to TSH levels, and consequently, thyrotoxicosis resulted in higher concentrations of IL-6 (OR 3.25)." (PMID 33765288, 2021). "Additionally, significant cytokines related to newly detected thyrotoxicosis were observed at the T2 time point, including IP-10, MDC, IL-6, and IL-4." (PMID 37629267, 2023). "The results revealed that IL-6 had an important function in the stimulation of the RANKL-RANK/OPG mechanism, which was strongly enhanced when the presence of accelerated bone turnover such as thyrotoxicosis." (PMID 36161625, 2022).
visceral leishmaniasis (23 papers, 2008 to 2025). A severe form of leishmaniasis characterized by irregular bouts of fever, substantial weight loss, swelling of the spleen and liver, and anemia (which may be serious). "IL-6 and IL-8 have consistently been identified as pathogenic, yet, in our study, only IL-8 emerged as a robust biomarker for severe or fatal kala-azar, although IL-6 levels were also elevated in fatal cases." (PMID 41003560, 2025). "IL-8 recruits neutrophils to organs parasitized by Leishmania, which in turn secrete cytokines such as IL-6, a mediator associated with disease severity in kala-azar." (PMID 41003560, 2025). "Among the variables analysed, death was significantly associated with IL-6 levels (coefficient = 1.0446, P = 0.015), suggesting that higher IL-6 levels increase the likelihood of death in patients with visceral leishmaniasis." (PMID 39670465, 2025). "In visceral leishmaniasis (VL) caused by L. infantum, higher IL-6 and IL-17 levels were found in male patients, as compared to females, which correlated with enhanced disease severity in males." (PMID 38359037, 2024). "The higher concentration of IL-6 in MCL agrees with a previous association with severity in visceral leishmaniasis." (PMID 33667232, 2021). "In experimental Visceral Leishmaniasis, IL-6 deficient mice showed enhanced control of L. donovani infection, suggesting a possible deleterious role for IL6, which was expressed >4-fold in HPs, compared to LPs." (PMID 27870860, 2016). "Elevated levels of IL-6 in plasma are associated with the severity of visceral leishmaniasis (VL)." (PMID 39670465, 2025). "It has been suggested that IL-6 may be associated with the activation and proliferation of plasma cells, contributing to the high production of immunoglobulins in individuals with active visceral leishmaniasis (VL)." (PMID 38455048, 2024). "In contrast, in symptomatic cases coinfected with HIV and kala-azar, elevated serum levels of IL-6, IL-10, and IL-17A were identified compared to healthy and asymptomatic controls." (PMID 41003560, 2025). "In this context, pretreatment serum levels of interferon-gamma (IFN-γ), tumor necrosis factor-α (TNF-α), IL-4, IL-6, IL-8, IL-10, and IL-27 are elevated in Brazilian individuals with untreated kala-azar." (PMID 41003560, 2025). "IL-6 contributes to disease severity and mortality in kala-azar, thereby contributing to the pathogenesis of coagulopathy in this condition." (PMID 41003560, 2025). "From the results of DisGeNET, the hub genes IL10, IL6, CXCL8, CSF2, IFNG, IL1B, and TNF were causing Visceral Leishmaniasis; IL10, IL4, CXCL8, IFNG, IL1B and TNF found to cause Cutaneous Leishmaniasis and Urban Cutaneous Leishmaniasis." (PMID 36989283, 2023). "IL-9 is a susceptibility factor in Leishmania infection by promoting detrimental Th2 responses, and elevated levels of IL-6 have been correlated with a high severity of visceral leishmaniasis." (PMID 32867338, 2020). "Patients with visceral leishmaniasis show high IL-6 serum levels during the evolution of the disease, as this cytokine acts by blocking macrophage activation, in addition to its microbicidal activity." (PMID 27051668, 2016). "Additionally, although the sample size is limited, a trend was observed linking elevated IL-6 levels to unfavourable clinical outcomes, emphasizing the relevance of IL-6 as a potential prognostic marker in cases of visceral leishmaniasis." (PMID 39670465, 2025). "The levels of IL-6 have been related to disease progression in visceral leishmaniasis." (PMID 35737357, 2022). "It is known that IL-6 along with TGF-β induce the development and maintenance of Th17 effector cells through upregulation of the IL-23 cytokine and its receptors, which have been associated with protection against visceral leishmaniasis." (PMID 35888991, 2022).
visceral leishmaniasis (continued). "Furthermore, multiple studies have shown a correlation between the high level of some cytokines, including IL-6, and the severity of visceral leishmaniasis and cutaneous leishmaniasis." (PMID 31134162, 2019). "Previous reports have shown that in vivo, pro-inflammatory cytokines such as IL-1β, IL-6 and TNF-α, as well as chemokines, are induced in the initial events of L. major and L. donovani, causative agents of cutaneous and visceral leishmaniasis infection in the Old World, respectively." (PMID 23497381, 2013). "The exacerbated profile of pro- and anti-inflammatory cytokines in patients with kala-azar appears related to disease worsening, particularly in the levels of IFN-γ, IL-6, IL-8, and IL-10." (PMID 41003560, 2025). "We employed ROC curve analysis to thoroughly assess the potential of IL-1β, IL-6, IL-8, IL-10, IL-12, and TNF-α as predictive biomarkers for identifying fatal cases of kala-azar." (PMID 41003560, 2025). "Based on observational data, it has been proposed that plasma IL-6 and IL-8, IFN-γ, IL-27, and soluble CD14 are the major mediators of the pathogenicity of kala-azar." (PMID 40732663, 2025). "In Sudan, individuals with kala-azar have high levels of IFN-γ, TNF-α, IL-4, IL-6, IL-10, IL-12, and IL-17A." (PMID 41003560, 2025). "Positive correlations were observed between the cortisol levels and the gene expression of factors related to promoting visceral leishmaniasis, such as arginase, IL-10, TGF-β, IL-1β, and IL-6." (PMID 34813597, 2021). "Even in non-severe kala-azar, we identified that levels of IL-6, IL-8, and IL-10 are promising biomarkers of early response to treatment." (PMID 41003560, 2025). "Our findings indicate that IL-6, IL-8, and IL-10 concentrations were similar in HIV-coinfected and non-HIV-coinfected kala-azar patients (p > 0.05)." (PMID 41003560, 2025).
age-related macular degeneration (22 papers, 2007 to 2025). Age-related loss of vision in the central portion of the retina (macula), secondary to retinal degeneration. "Recently, a study has associated treatment with Bevacizumab in age-related macular degeneration with IL-6 cytokine, and suggested that IL-6 could be a major marker of treatment response and resistance." (PMID 29971005, 2018). "Higher levels of the systemic inflammatory markers CRP and IL-6 are independently associated with progression of age-related macular degeneration (AMD)." (PMID 17374166, 2007). "Overall, our data indicate that aqueous IL-6 and aqueous IL-8 may be important markers of treatment response or resistance in wet macular degeneration." (PMID 39325472, 2024). "Aqueous IL-6 may be an important marker of treatment response or resistance in wet macular degeneration." (PMID 25110587, 2014). "Both DR and age-related macular degeneration are chronic inflammatory diseases that involves the activation of the microglia, monocytes-macrophages, neutrophils, and lymphocytes as well as the secretion of inflammatory mediators, including IL-6, TNF-α, MCP-1, and VEGF." (PMID 36712506, 2022). "IL-6 has emerged as a key molecular mediator in this process, with systemic levels significantly elevated in late-stage age-related macular degeneration (AMD), including geographic atrophy and neovascular subtypes, while showing only marginal association with early AMD." (PMID 40657159, 2025). "Since increased senescent cells and secretion of IL-6 and VEGF are involved in age-related macular degeneration pathogenesis, our results support that carotenoid supplementation has a potential role in protecting the eyes from the deleterious effects of excessive BL exposure." (PMID 40151609, 2025). "Unlike Vascular Endothelial Growth Factor (VEGF) -inhibitors used intravitreally for treating exudative age-related macular degeneration, which have a short half-life in the eye of just a few days, no similar data exists for the anti-IL-6 antibody." (PMID 39497001, 2024). "Recently, IL-6 expression was reported to be elevated in RPE cells and stroma of patients with exudative age-related macular degeneration (AMD), and downregulation of IL-6 reduced subretinal fibrosis in mice models." (PMID 33255431, 2020).
autoimmune hepatitis (22 papers, 2011 to 2026). Hepatitis caused by autoantibodies. "Proinflammatory cytokines such as interferon(IFN)-γ, interleukin(IL)-12, tumor necrosis factor(TNF)-α, IL-6 and IL-23 have been implicated in the pathogenesis of autoimmune hepatitis." (PMID 35547732, 2022). "Intriguingly, reports have shown that patients with autoimmune hepatitis (AIH) exhibit the IL-6 -174 GG genotype and have significantly higher IL-6 polymorphism levels." (PMID 39958350, 2025). "Pretreatment with resveratrol ameliorated the pathologic effects of ConA-induced autoimmune hepatitis and significantly inhibited IL-2, IL-6, TNF-α, Shh, Gli-1, and Ptc." (PMID 26089871, 2015). "Recent research has shown that autoimmune hepatitis was associated with the release of large amounts of inflammatory cytokines, such as TNF-α, IL-6, IL-1β and IFN-γ, leading to apoptosis and necrosis in liver pathology." (PMID 25761053, 2015). "Recently, studies have reported that Con A-induced autoimmune hepatitis is largely mediated by the release of inflammatory cytokines such as IL-2, IL-4, IL-6, IL-10, IL-12, TNF-α and IFN-γ." (PMID 24498418, 2014). "It will be of clinical importance to define the role of IL-6 and the “MDSCs” in T cell-mediated liver injury during viral hepatitis or autoimmune liver diseases." (PMID 21394214, 2011). "One study demonstrated that LDN protects against the inflammatory response induced by autoimmune hepatitis, which may be related to its ability to suppress IL-6 and TNF-α secretion and interfere via modulation of the TLR4/NF-ƙB signalling pathways." (PMID 38720250, 2024). "We aimed to determine whether resveratrol could inhibit the expression and release of cytokines such as TNFα, IL-2, and IL-6 in ConA-induced autoimmune hepatitis." (PMID 26089871, 2015). "Restoring the imbalance among Th17 cells and Tregs by interrupting interaction between IL-17 and IL-6 may be an effective therapeutic target for autoimmune liver diseases." (PMID 21526159, 2011). "In contrast, IL-6/gp130 signaling may aggravate liver damage in autoimmune hepatitis." (PMID 37391912, 2023). "A study of cytokine levels in children with autoimmune hepatitis discovered a correlation between the levels of TNF-α, IL-6, and IL-8 and disease activity in patients with type 1 AIH." (PMID 28299346, 2017). "Several studies show that the release of inflammatory cytokines is involved in autoimmune hepatitis, including IL-1β, TNF-α, IFN-γ, and IL-6, giving rise to the development of liver injury." (PMID 27293314, 2016). "In a previous study of toxic autoimmune hepatitis, IMMP decreased levels of IL-6 in the serum of rats under the same scheme of treatment." (PMID 25324698, 2014). "Pretreatment with ethyl pyruvate ameliorated the pathological effects of Con A-induced autoimmune hepatitis and significantly decreased the levels of TNF-α, IL-2, IL-6 and IL-1β at 3h and 6h and the level of HMGB1 at 6h and 24h post injection." (PMID 24498418, 2014). "Taken together, these results indicated that ethyl pyruvate protected against Con A-induced autoimmune hepatitis by decreasing both early (TNF-α, IL-2, IL-1β and IL-6) and late (HMGB1) cytokine expression in mice." (PMID 24498418, 2014). "Thus, the key target genes for autoimmune hepatitis treatment mainly included AKT1, IL6, VEGFA, CASP3, JUN, MYC, etc.." (PMID 36558908, 2022). "IL-2, IL-6, TNF-α and IL-1β were released starting at 3h after administration of Con A, and inhibition of the release of these cytokines attenuates the Con A-induced autoimmune hepatitis." (PMID 24498418, 2014). "The purpose of our study was to determine whether ethyl pyruvate could inhibit the expression and release of both early (TNF-α, IL-2, IL-6, IL-1β) and late (HMGB1 ) cytokines in Con A-induced autoimmune hepatitis." (PMID 24498418, 2014).